IL17A (interleukin 17A)
Diseases named in the same sentence as IL17A in open-access papers (continued):
Sharing a sentence is not in itself a finding about the gene and the disease.
COVID-19 (continued). "At very high exposure level, COVID-19-positive individuals demonstrated a continuous increase in IFN-γ, IL-2, IL-6, and IL-17A, while TNF peaked early and IL-10 showed minimal expression." (PMID 40406109, 2025). "Critical COVID-19 cases showed higher levels of inflammatory markers (Bilirubin, D-dimer, PCR, and urea, as well as IL-8, IL-10, TNF-α, INF-α, IL-1β, IL-17A, IL-23, IL-6) than moderate and severe groups." (PMID 39861879, 2025). "We found several factors that clearly can be part of driving the inflammatory state in COVID-19 patients, such as CHUK/IKK-α, and IL17A." (PMID 41227320, 2025). "In fact, when compared to controls, amniotic fluid from COVID-19-affected pregnancies demonstrated elevated levels of several pro-inflammatory cytokines, including IL-12 p40, CCL4, CCL7, CCL13, TNF, IL-1a, IL-17A, and IL-17E." (PMID 39390219, 2024). "Subsequently, we screened their reactivity with peripheral blood mononuclear cells (PBMCs) of COVID-19 patients with moderate or severe disease, as well as healthy donors (HDs), by measuring IFN-γ and IL-17A production." (PMID 39066169, 2024). "(C) Relative expression of IFNγ, IL-17A, TGFβ, and IL-10 genes in peripheral blood CD3+ CD4+ cells from COVID-19 patients (moderate or severe) and healthy control (HC)." (PMID 37523305, 2023). "Compared with the control group, there was extensive cytokine/chemokine correlations centered on IL-17A, IL-10, IL-6, CCL2, CXCL8, CXCL9 and CXCL10 and fewer correlations with IL-1β in the COVID-19 patients at baseline." (PMID 37662953, 2023). "More recently, it has been confirmed, in Egypt, in a pediatric cohort of mixed COVID-19/MIS-C individuals, (n = 31) that IL-17A was upregulated." (PMID 36851285, 2023). "In co-infected patients:↑ TNF-α, MIP-1β, and IL-9 compared with COVID-19-only.↑ TNF-α, IL-1β, IL-17A, IL-5, FGF-basic, and GM-CSFcompared with TB-only.↓ specific response to SARS-CoV-2 and Mtb." (PMID 37662901, 2023). "The RS between activation marker concentrations and the severity of COVID-19 are calculated by training data set Z2KP, where the activation markers are IL-17a, IL-2, GATA3, IFN-γ, IL-4, IL-10, PD_1, CD40L, RORγt, CTLA_4, CCR7, TNF-α and IL-6, respectively." (PMID 36845115, 2023). "For instance, lung tissue specimens obtained from COVID-19 patients were enriched for cells co-expressing CCR6 and IL17A and also had high levels of IL-6, IL-17A, GM-CSF, and IFNγ found in BALF." (PMID 38179278, 2023). "From the 44 DEPs, all of the proteins were upregulated in patients with COVID-19 compared with their DCs, except TRAF2 and IL17A." (PMID 37047248, 2023). "In hospitalized patients with mild-to-moderate COVID-19, the combination of SOC with anti-IL-17A or anti-IL-6R therapy were superior or comparable to the combination with JAK1/JAK2 inhibitor, and all three were superior to SOC alone." (PMID 36001576, 2022). "In relation to the groups with SIgA, increased levels of IL-10, IL-13, IL-17A, and IFN-α were found in the COVID-19 group as compared to the values observed in the control group." (PMID 35686128, 2022). "CCL22, IL-12/IL-23p40, IL-5, IL-17A and TNF-β levels, on the other hand, were greater in mild or moderate COVID-19 patients than in severe COVID-19 patients (P < 0.05)." (PMID 35958594, 2022). "In agreement, we have reported the elevation of a wide spectrum of cytokines/chemokines including IL-6, TNF-α, IL-10, IL-12p70, IL-4, IL-15, GM-CSF, IL-17a, IL-8, IP-10, MCP-1, MIP-1α in the plasma of COVID-19 patients." (PMID 35284964, 2022). "The IL17A/IL17F gene region, which had the lowest P value in the GWAS comparing severe and mild COVID-19 patients in Japanese, met the genome-wide significance level as a result of an integrated analysis with the international meta-GWAS." (PMID 35264675, 2022). "Cytokine profiles of PBMCs showed significantly lower levels of GM-CSF, IFN-γ, IL-6, IL-9, IL-10, IL-17A, and TNF-α (p < 0.0001) in COVID-19 ICU patients." (PMID 36363785, 2022).
COVID-19 (continued). "Considering the discovery of CXCL8 as an IL-1β–induced protein, we found that COVID-19 BAL fluid levels of CXCL8 and IL-1β correlated positively with each other and with levels of IL-17A." (PMID 34793331, 2022). "In contrast, G-CSF, IL-1RA, IL-17a, IL-1b, INFγ, MCP3 and TNFα were undetectable or negligible in the serum and CSF of both the HC and the COVID-19 group." (PMID 35479062, 2022). "Particularly in the COVID-19 groups, IL-6 presented a positive correlation with IFN-γ and also IL-12p70 presented a positive correlation with IL-17A." (PMID 35686128, 2022). "The lung tissues of patients with COVID-19 were enriched with CCR6 and IL-17A co-expressing cells, and high concentrations of IL-6, IL-17A, GM-CSF, and IFNγ were found in the liquid fraction of BALF." (PMID 35632823, 2022). "Such interleukins as IL-1β, IL-6, IL-17A, TNFα, and monocyte chemoattractant peptide (MCP)-1 were identified in patients with severe COVID-19." (PMID 35213582, 2022). "A correlation matrix for IL-22R+ expressing myeloid cell subsets with the ex vivo IL-22, IL-17A, IFN-γ, granzyme B and perforin expressions on NK and T cells was generated to evaluate a possible relationship between these parameters in COVID-19 patients." (PMID 35422799, 2022). "In contrast, the highest contributors to dimension 1 were IL-21, IL-2, IL-1b, IL-17A, GM-CSF, IFN-γ, IL-7 and CCL3, and these cytokines were significantly decreased in acute COVID-19 patients in comparison to HC." (PMID 34572439, 2021). "In contrast, IL-1β, IL-4, IL-5, IL-12p70, IL-13, IL-17A, CCL11, and VEGF levels predicted severe COVID-19." (PMID 33995342, 2021). "In this study, we investigated the effect of pre-analytical sample handling variations on levels of COVID-19-relevant cytokines IFN-γ, IL-10, IL-12p70, IL-17A, IL-6 and TNF-α." (PMID 34289718, 2021). "As in the previous report, elevated IL-17A levels were observed in AOSD patients, even higher than those in severe COVID-19." (PMID 34367188, 2021). "Our present results identified obvious elevations of various cytokines in patients with severe COVID-19, including IL-1α, IL-1β, IFN-γ, TNF-α, IL-2, IL-4, IL-6, IL-10, and IL-17A." (PMID 34113636, 2021). "Our results showed that critically ill COVID-19 patients had increased serum levels of IL-1β, IL-1RA, IL-6, IL-9, and CXCL10, and lower levels of IL-2 and IL17A as compared to healthy volunteer donors." (PMID 33995342, 2021). "IL17-A and IL17-F are increased in COVID-19 patients [TE90], and genes related to IL17 signalling are significantly enriched in the severe-fatal group [TE96]." (PMID 34876157, 2021). "Circulating MAIT and iNKT cells from COVID-19 patients produced less IFN-γ and higher IL-17A compared with cells from healthy donors." (PMID 35381137, 2021). "Tissue expression increasing of IL-8/IL-17A and a higher number of neutrophils were identified in samples from the H1N1 group compared to the COVID-19 group." (PMID 33868301, 2021). "Active AOSD patients share features of hyperinflammation and cytokine storm with severe COVID-19 patients but possess a distinct cytokine profile, including elevated IL-18, IL-6, IFN-γ, and IL-17A." (PMID 34367188, 2021). "We also observed the upregulation of IFN-γ, CCL2, IL-8, IL-12p70, IL-17a and TNF-α in COVID-19 patients compared to healthy controls." (PMID 34386007, 2021). "It was reported that plasma cytokines IFN-γ, IL-10, IL-12p70, IL17A, IL-6 and TNF-α levels are increased in COVID-19 patients admitted to the ICU when compared with healthy controls." (PMID 34289718, 2021). "The present data indicate that DPSC administration might be effective in patients with COVID-19-induced hyper-inflammation, due to the inhibition in the production of several cytokines by activated T lymphocytes, namely, IFNγ, TNFα, IL-2, IL-9, IL-10, IL-17A, IL-18, IL-21, and IL-27." (PMID 33634100, 2020).
COVID-19 (continued). "Among the statistically significant reduced cytokines exhibited by patients with COVID-19 compared to influenza patients were interferon-γ (IFN-γ), MIG, IL-1RA, IL-2R, G-CSF, IL-17a, IL-9, and MIP-1α." (PMID 33187979, 2020). "Higher percentages of CD4+ T cells producing IFNγ, TNFα, IL-2, and IL-17A and CD8+ T cells producing IL-2 and IL-17A have been detected by flow cytometry in PBMCs from COVID-19 patients vs. healthy controls after in vitro stimulation." (PMID 33634100, 2020). "Additionally, higher levels of inflammatory cytokines IL-8, IL-17A, and IL-23 were noted in these women, indicating a potential link between inflammation and PPH in the context of COVID-19, necessitating further research." (PMID 40303405, 2025). "We observed higher levels of bilirubin, D-dimer, C-reactive protein, urea, and plasmatic cytokines, such as IL-1β, IL-6, IL-8, IL-10, IL-17A, IL-23, TNF-α, and IFN-α in individuals with the critical form of acute COVID-19 compared to individuals with the severe and/or moderate WHO clinical forms." (PMID 39861879, 2025). "In the COVID-19+ group, as expected, significantly increased levels of proinflammatory cytokines/chemokines including INF-α2, INF-γ, MCP-1, IL-6, IL-12p70, IL-17A, IL-18, IL-23 and IL-33 were detected, while the level of IL-10, an anti-inflammatory cytokine was also elevated as compared to controls." (PMID 40303405, 2025). "In this study, interestingly, mild/asymptomatic COVID-19+ pregnant women exhibited significantly elevated levels of proinflammatory cytokines/chemokines such as INF-α2, INF-γ, MCP-1, IL-6, IL-12p70, IL-17A, IL-18, IL-23, and IL-33, and the anti-inflammatory cytokine IL-10." (PMID 40303405, 2025). "In line with this, several lines of research suggest that post-COVID-19 may involve persistent (neuro) inflammation, indicated by increased levels of pro-inflammatory cytokines such as TNF-α, IL-1β, and IL-17A." (PMID 40686929, 2025). "IL-17F, but not IL-17A, was significantly elevated in people with COVID-19 compared to healthy controls and with more severe disease." (PMID 39493750, 2024). "The presence of chronic inflammation in hypertensive patients may explain our observation of increased circulating levels of IL-4, IL-5, IL-13, IL-17A, and TNF-β levels during hospitalization in patients with COVID-19 and hypertension in the present study." (PMID 39685774, 2024). "This does not mean that IL-17A is absent in severe COVID-19 or that it does not play a role in the pathobiology of the disease." (PMID 39493750, 2024). "Th17 cells from approximately 50% of individuals with PCC had no capacity to express IL-17A and IL-22, similar to individuals with critical COVID-19, which would prevent clearing extracellular pathogens." (PMID 39257580, 2024). "Specifically, increased levels of various chemokines [C-X-C motif chemokine 1 (CXCL1), CXCL5, CXCL6, CXCL11] and cytokines [interleukin-17A (IL-17A), cluster of differentiation 40 (CD40), IL-6] were observed in the MIS-C group compared to the pediatric COVID-19 group." (PMID 39457139, 2024). "In contrast, IL-17A levels were not significantly elevated in the COVID-19-positive participants from the ward or ICU compared to the healthy controls." (PMID 39493750, 2024). "Although Il-17A and IL-17F are known to signal through the same receptor IL-17RA/RC, the results obtained here from the analysis indicate that IL-17F and not IL-17A was significantly enriched in the plasma of patients with severe COVID-19." (PMID 39493750, 2024). "Compared with those in healthy volunteers, the concentrations of interleukin (IL)-6 (median 27.6 pmol/L), IL-8 (1045.1 pmol/L), IL-17A (0.8 pmol/L), IL-25 (1.5 pmol/L), and IL-31 (42.3 pmol/L) were significantly greater in the ELF of COVID-19 patients than in that of volunteers." (PMID 38654351, 2024).
COVID-19 (continued). "Results from the hamster challenge study demonstrated a strong anti-inflammatory potential of A64, as the mRNA expression of inflammatory cytokines such as IL-6, IL-17A, and TNF-α (all of which have been strongly correlated with COVID-19 severity) was significantly reduced." (PMID 37765142, 2023). "Moreover, the lung tissues in COVID-19 patients were enriched in CCR6- and IL17A-co-expressing cells." (PMID 37626620, 2023). "However, HD patients with COVID-19 symptom worsening showed up-regulation (more than 2.5-fold increase) of GM-CSF, IFN-γ, IL-1β, IL-2, IL-6, IL-17A and IL-21, and down-regulation of TNF-α and IL-8 serum levels after the dialysis procedure." (PMID 36675231, 2023). "Moreover, lung tissues collected from COVID-19 patients were enriched in CCR6 and IL-17A co-expressing cells." (PMID 37626620, 2023). "IL-27, IL-17A and IL-12 plasma levels increased in COVID-19 non-HD patients depending on disease severity, whereas no significant dynamics were detected in HD patients." (PMID 35265078, 2022). "The cytokine profile obtained was adequate because it mainly involved anti-viral cytokines IL-12, IL-17A, and IL-2, not cytokines participating in the COVID-19 cytokine storm, such as IL-6 or IL-10." (PMID 35440789, 2022). "Previous reports on immune response to SARS-CoV-2 have shown that T cell response is greatly diverse, as T cells from COVID-19 patients can secrete TH1 cytokines, including IFN-γ and TNF, TH17 cytokines, including IL-17A, TH2 cytokines, including IL-4, and others, including IL-2 and CD107a." (PMID 35386702, 2022). "On the other hand, serum levels of cytokines in COVID-19 ICU patients showed a significant increase in the production of GM-CSF, IFN-α, IL-2, IL-4, and IL-6 and a significant decrease in the levels of IFN-γ, IL-5, IL-12, IL-17A, and TNF-α." (PMID 36363785, 2022). "Despite the underlying causes of COVID-19 and regardless of the patient’s course of disease, MAIT cells were highly activated and produced large amounts of proinflammatory cytokines such as IL-17A and TNF-a." (PMID 36034704, 2022). "There were reduced frequency and an activated phenotype of circulating MAIT cells in COVID-19 patients regardless of disease severity, as demonstrated by high levels of IL-17A, TNF-α, CD38, CD69, and HLA-DR expression." (PMID 36034704, 2022). "This supported the conclusion that CoVPSA might be a relevant antigen to incorporate in COVID-19 vaccines to induce high levels of anti-viral cytokines, such as IFN-γ, IL-17A, and IL-2." (PMID 35440789, 2022). "Moreover, a positive correlation was seen between levels of IL-1β or IL-17A and CXCL8 in the BAL fluid of the patients with COVID-19." (PMID 34793331, 2022). "We found that acute COVID-19 neutrophils secreted reduced G-CSF, MIP-1α, MIP-1β, MCP-1, IL-2, SDF-1α, IL-9, IL-17A, IL-18, IL-20 and IL-23 levels, but secreted increased soluble PD1, IP-10 and MIP-2α levels compared to rec-phase and healthy neutrophils upon bacterial challenge." (PMID 35007290, 2022). "In particular, adults with severe acute COVID-19 inflammation had higher levels of IL-7 and IL-8 than pediatric patients with KD and MIS-C, while IL-17A and endothelial and smooth muscle cell-derived neuropilin-like (ESDN) were higher in patients with KD than in patients with MIS-C." (PMID 35558368, 2022). "While some have suggested IL-17 is significantly elevated in mild COVID-19 patients compared to those that are not infected, other studies have shown upregulated IL-17A in COVID-19 patients regardless of disease severity." (PMID 35572514, 2022). "However, additional investigation into the lung-specific cellular source of the proinflammatory cytokines typical of severe COVID-19, including IL-6, tumor necrosis factor–α (TNF-α), IL-1β, and IL-17A, is needed." (PMID 33622974, 2021).
COVID-19 (continued). "Our data indicate that MAIT cells are highly activated in patients with COVID-19, irrespective of the course of disease, and express high levels of proinflammatory cytokines such as IL-17A and TNFα ex vivo." (PMID 33546489, 2021). "Another explanation may be based on the observation that pediatric patients have higher serum concentrations of IL-17A and IFN-γ shortly after clinical presentation of COVID-19." (PMID 33921679, 2021). "Of note, flow cytometric analysis of unstimulated whole-blood samples revealed no significant enrichment in the percentage of IL-4+ or IL-17A+ lymphoid cell populations in COVID-19 patients relative to HVs." (PMID 33232303, 2021). "PIMS-TS children had significantly elevated levels of cytokines, IFNγ, IL-2, TNFα, IL-1α, IFNα, IFNβ, IL-6, IL-15, IL-17A, GM-CSF, IL-10, IL-33 and IL-Ra; elevated chemokines, CCL2, CCL19, CCL20 and CXCL10 and elevated VEGF, Granzyme B and PDL-1 in comparison to COVID-19, seropositive and controls." (PMID 33813138, 2021). "To investigate the role of cytokines and chemokines in the inflammatory status of COVID-19 and MIS-C, we measured plasma levels of IL-1ß, IL-2, IL-4, IL-5, IL-6, IL-10, TNF-α, IL-17A, IFN-α, IFN-γ, CXCL10/IP-10, CXCL8/IL-8, CXCL9/MIG, CCL5/RANTES, and CCL2/MCP1." (PMID 33841438, 2021). "Therefore, this network also displays the contribution of increased pro-inflammatory molecules or signaling pathways (IL1B, IL6, IL8, IL17a) and upregulated chemokine signaling (CXCR4 signaling, CCL5) observed in severe COVID-19 outcomes." (PMID 33941085, 2021). "Notably, the levels proinflammatory cytokines such as IL-1β, IL-17A, IL-2, and RANTES remained elevated in COVID-19 patients at the early convalescent phase, particularly in those with prior cardiovascular risk, compared to healthy controls." (PMID 33752798, 2021). "Our findings are consistent with a recent report in which IFN-γ, but not IL-17A, was detected in T cells from patients with COVID-19 that were stimulated with peptide from the virus." (PMID 32958614, 2020). "The stimulation of PBMCs from COVID-19 patients with S protein peptides resulted in production of effector or Th1 cytokines (IFN-γ, TNF-α, and IL-2) and, to a lesser extent, Th2 (IL-5, IL-13, IL-9, and IL-10) and Th17 (IL-17A, IL-17F, and IL-22) cytokines." (PMID 32916812, 2020). "In this study, we monitored the levels of ACE2, TMPRSS2, IL-17A, ADAM-17, VD, and AP in NPS, serum, and saliva to assess their impact on health status, further supporting the need for multi-biomarker approaches in evaluating COVID-19’s effects on the immune system." (PMID 40003732, 2025). "Our results show an association between IL-17F and COVID-19 severity in the large BQC19 cohort rather than IL-17A, which may provide an explanation for the lack of efficacy when targeting IL-17A alone." (PMID 39493750, 2024). "In contrast to COVID-19, which showed markedly elevated plasma concentrations of 11 SMs, we observed decreased levels of several SMs, mainly pro-inflammatory cytokines (e.g., IFN-γ, IFN-α2, TNF-α, IL-7, IL-17A, and IL-15) in both the remission and acute phases of TTP." (PMID 39337495, 2024). "Interestingly, we did not detect higher abundances of genes in the IL17A gene module among participants with severe COVID-19 and detectable Candida spp." (PMID 38687064, 2024). "In addition, Th17 cells from more than 50% of individuals with PCC showed no capacity to express cytokines such as IL-17A and IL-22, similar to participants with critical COVID-19." (PMID 39257580, 2024). "However, this underscores that an IL17A-induced epithelial cell state represents a shared feature of individuals who develop severe COVID-19 and is correlated with the absence of robust interferon-induced anti-viral responses." (PMID 38687064, 2024).